MIR3913-1 (microRNA 3913-1)
Synonyms: hsa-mir-3913-1; mir-3913-1
Gene: MicroRNA gene on chromosome 12 (69,584,722 to 69,584,823, reverse strand). Ensembl gene ENSG00000264405.
Homologues: Orthologues: chimpanzee MIR3913-1 (100% identical).